GATA3 (GATA binding protein 3)
Diseases named in the same sentence as GATA3 in open-access papers (continued):
Sharing a sentence is not in itself a finding about the gene and the disease.
prostate carcinoma (continued). "Furthermore, while this manuscript was under review, another study was published demonstrating that the GATA3-driven expression of miR-503 represses ZNF217 in prostate cancer." (PMID 27539783, 2016). "A literature review focusing on AR, GATA3 and ZNF622 regulation of glycogenes identified a single paper reporting AR binding to a B3GNT5 promoter, using semi-quantitative PCR with ChIP in prostate cancer cell line LAPC-4." (PMID 34283051, 2021). "For both promoters and enhancers we also identified a subset of disruptive variants that target response elements for factors of special interest to prostate cancer, namely AR, FOXA1, NKX3-1, TCF7L2, MYC, GATA1 and GATA3." (PMID 24497837, 2014). "GATA-3 is a reliable marker to distinguish urothelial from prostatic carcinomas, typically resulting negative in PAs." (PMID 37374005, 2023). "Methylation of the IL-4 gene was moderately to highly elevated in prostate cancer cells and increased DNA methylation of GATA3 was observed in androgen negative prostate as compared to androgen positive cells." (PMID 28969068, 2017). "In addition, miR‐503 accompany with GATA3, targets ZNF217 and suppresses prostate cancer." (PMID 38173189, 2024). "However, GATA3 is not expressed in any human prostate cancer cell lines at mRNA or protein levels (unpublished data)." (PMID 27374105, 2016). "In cultured prostate cancer cell lines, GATA2 has been shown to function as a pioneer factor for AR genomic binding and function, while surprisingly GATA3 is not expressed." (PMID 27374105, 2016).
colitis (29 papers, 2015 to 2024). Inflammation of the colon. "To analyse the influence of GATA3 in colitis-associated tumour development, we used conditional GATA3-floxed mice that were crossed to Cd4cre mice." (PMID 35793807, 2022). "Again, they found that only GATA3 overexpression led to more severe colitis with enhanced levels of IL-13, which was causatively involved in the development of colitis." (PMID 33371444, 2020). "In an in vivo study using an oxazolone-induced colitis model, leptin-deficient ob/ob mice were protected from colitis by suppressing expression of the key transcription factors such as T-bet and GATA-3 under Th1 and Th2 polarization." (PMID 33334069, 2020). "While TNBS-induced colitis was associated with a change of the Th profile (notably an increase in the Tbet/Gata3 ratio in the spleen), the colitis-inhibition induced by ferric iron was associated with a limitation of the splenic Th profiles perturbation." (PMID 31370166, 2019). "Furthermore, we analysed colitis-associated tumours and detected even higher levels of Th9-associated factors and marked correlations between GATA3, SPI.1, and IL-9 mRNA levels, suggesting the relevance of Th9 cells in these patients." (PMID 35793807, 2022). "Moreover, they confirmed that GATA3 has a pathogenic role in this context since the conditional deficiency of GATA3 in T cells protected mice from oxazolone colitis." (PMID 33371444, 2020). "Finally, another study revealed that GATA3 transgenic mice exhibited more pronounced colitis induced by DSS, a phenotype associated with a higher intestinal production of IL-13." (PMID 33371444, 2020). "Conditional GATA3 deficiency in T cells prevented experimental colitis in mice." (PMID 31068803, 2019). "Indeed, IL-9 is significantly reduced in oxazolone-induced colitis when GATA3 is deficient in T cells." (PMID 29910812, 2018). "Moreover, the mucosal expression of GATA3 was positively associated with disease activity in adult patients with UC and correlated with the production of inflammatory cytokines in both patients with UC and in models of experimental colitis." (PMID 32369982, 2020). "Genetic studies in mice illustrated that ST2+ Tregs depend on a Sted2d‐Gata3 axis to suppress Th2 cells during colitis." (PMID 38707998, 2024). "Taken together, these results suggest that treatment with rTsPmy up-regulates GATA3 expression in Foxp3+ Tregs in the Th2 environment, possibly enhancing the stability of Tregs in cLP of mice with colitis." (PMID 34336843, 2021). "In this study, we showed that treatment with rTsPmy significantly increased GATA3 expression in Foxp3+ Tregs in cLP of mice with colitis." (PMID 34336843, 2021). "Further investigation showed that rTsPmy increased the GATA3+Helios+ tTregs subset in cLP of mice with colitis." (PMID 34336843, 2021). "At the mRNA level, colitis induced a significant increase in Tbet and GATA-3, while the RORγt expression was significantly reduced." (PMID 34248633, 2021). "Genetic ablation of Gata3 in mouse T cells was shown to contribute to significant inhibition of IL-9 expression in oxazolone-induced colitis." (PMID 32369982, 2020). "The contribution of GATA3 in colitis has been investigated in several publications with data from mice and humans, and especially from UC patients." (PMID 33371444, 2020). "After oxazolone challenge, GATA3 in WT rose dramatically in accordance with the Th2 nature of oxazolone-induced colitis." (PMID 32541827, 2020). "The authors also demonstrated that the inhibition of GATA3 transcription by hgd40 was able to ameliorate colitis also in TNF receptor (TNFR) double-knockout mice." (PMID 31068803, 2019). "Treatment with rBmaCys in DSS-induced colitis mice slightly decreased the levels of GATA-3 in the colon cells, however, there was a significant decrease in the expression of ROR-γ in the colon cells after rBmaCys-treatment." (PMID 31683524, 2019).
colitis (continued). "A study conducted with intestinal biopsies of UC patients as well as murine models of colitis showed a correlation between the expression of the transcription factor GATA3 and the production of inflammatory Th2 and Th9 related cytokines." (PMID 31068803, 2019). "Similar observations were also made in biopsies obtained from patients suffering from active UC, in which GATA3 expression correlated with disease activity, and in mice with colitis induced by oxazolone treatment." (PMID 30319608, 2018). "In a murine models of UC (DSS and oxazolone-induced UC), overexpression of GATA3 accelerates acute colitis in contrast to overexpression of T-bet or RORγt." (PMID 29910812, 2018). "This is supported by the fact that Treg-specific Gata3 conditional knockout (cKO) mice develop a spontaneous systemic inflammatory disorder and Gata3 cKO Tregs are defective in their suppressive function and fail to prevent T cell mediated colitis." (PMID 37197653, 2023). "GATA3 expression among Foxp3+ Tregs was assessed in this study and results showed that the proportion of Foxp3+ Tregs expressing GATA3 was significantly elevated in cLP from rTsPmy-treated mice with colitis compared with mice with colitis that received only PBS." (PMID 34336843, 2021). "In this study, mRNA expression levels of Tbet and GATA-3 were significantly increased in T cell transfer colitis mice (colitis + vehicle group) which could be normalized after treatment with UAMC-00050 (colitis + UAMC-00050 group)." (PMID 34248633, 2021). "Co‐transfer of Gata3‐negative Tregs from OX40cre Gata3fl/fl, or Foxp3EGFP‐cre Gata‐3fl/fl mice, with naive T cells into Rag1−/− recipients induces severe colitis and weight loss, suggesting that Tregs use Gata3 to limit tissue inflammation." (PMID 32463116, 2020). "In our experiment, seven days after inducing a moderate inflammatory response, the analysis of Tbet and Gata3 expression in the spleen confirmed the Th1 profile, but also the main role of Tbet in the colitis, as illustrated by the strong increase of the Tbet expression." (PMID 31370166, 2019). "Here, we show that treatment of mice with IL-2/IL-2 antibody (JES6-1) immunocomplex during DSS-induced colitis induced Foxp3+ Treg expansion, but also potently stimulated GATA3+ type 2 innate lymphoid cell (ILC2) proliferation and high-level expression of IL-5." (PMID 30930900, 2019). "In this report, we show that treatment of mice with IL-2/JES6-1 immunocomplex during DSS-induced colitis promoted Foxp3+ Treg expansion, but also potently stimulated GATA3+ group 2 innate lymphoid cell (ILC2) proliferation and high-level expression of IL-5 in the colon." (PMID 30930900, 2019). "Thus, the enhanced expression of GATA3 observed in the present colitis study indicates a local immune response biased toward the Th2-type which is supported by the H4R genotype of the transferred eosinophils." (PMID 30319608, 2018). "Several studies have suggested that overexpression of GATA-3 in T cells could markedly aggravate the severity of DSS-induced colitis in mice and that IL-4-deficient mice develop less severe DSS-induced colitis than WT mice do." (PMID 27110068, 2016). "Moreover, overexpression of GATA3 in T cells accelerates colitis induced in mice by DSS feeding." (PMID 30319608, 2018). "Nevertheless, BM-MSC treatments downregulated Nos2, Arg1, Gata3, Mrc1 and Hmox1 which were upregulated in Winnie mice and IBD patients; but are reportedly also upregulated by MSCs in chemical models of colitis." (PMID 38503815, 2024). "These mice, with a T cell-specific GATA3 deletion, were equally inflamed compared with littermate controls during the first two DSS cycles, but showed augmented colitis activity during the third cycle of DSS." (PMID 35793807, 2022). "The results indicate that the rTsPmy-induced Th2 environment facilitates GATA3 expression in Tregs, and therefore increases the stability of Tregs in the colon to exert a suppressive function on DSS-induced colitis." (PMID 34336843, 2021).
colitis (continued). "Several genes such as Gata3, Itk, Ccl8, Ccl22, Ccr4, Crlf2, Il9r, Il1rl1, and Arg2 are regulated concordantly in T-cell transfer colitis, acute DSS colitis and the time point representing high inflammation in the DSS time course." (PMID 34136502, 2021). "Blocking GATA3 with a specific DNAzyme reduces inflammation histologically in a 2,4,6-trinitrobenzene sulfonic acid (TNBS)-induced colitis murine model." (PMID 34581755, 2021). "Intrarectal administration of a GATA3 specific DNAzyme (hgd40) significantly ameliorated colitis in oxazolone and 2,4,6-trinitrobenzene sulfonic acid (TNBS)-mediated colitis models." (PMID 31068803, 2019). "GATA-3 and Foxp3 were expressed more highly in mice of group TNBS-rSjcystatin than in mice with colitis, while a low expression of T-bet was seen after rSjcystatin treatment except that RORγ(t) stayed nearly the same in those two experimental groups." (PMID 26728323, 2016). "Our results showed that the colonic protein and mRNA expression levels of T-bet and ROR-γt significantly decreased but GATA-3 and Foxp3 expressions were enhanced in colon after HQT treatment in colitis rats." (PMID 26347453, 2015). "The Th1 transcription factor T-bet plays a critical role in the development of Th1-driven colitis due to the high expression levels of IFN-γ, while GATA3 is an essential master regulator of Th2 cells for the induction of IL-4, IL-5, and IL-13." (PMID 26347453, 2015). "Accordingly, there was no significant change in the expression of GATA3 or IL-10 in the DSS-induced colitis group." (PMID 32034203, 2020). "STAT6, GATA3, and SMAD proteins are also required for Th9 differentiation and may be involved in Th9-mediated colitis." (PMID 29910812, 2018). "Besides, UAMC-00050 partially reversed the colitis-induced increase in Tbet and GATA-3 expression without affecting controls." (PMID 34248633, 2021). "Interestingly, IL-23 inhibits the expression of Gata3 and ST229, suggesting that the upregulation of IL-23 in colitis might limit T-cell responsiveness and Treg differentiation in response to IL-3329." (PMID 28404987, 2017).
melanoma (28 papers, 2008 to 2025). A malignant, usually aggressive tumor composed of atypical, neoplastic melanocytes. "Also, as DCs were not sufficiently represented in the available human cutaneous melanoma data sets, further studies will be required to investigate TSLPR-expressing DCs and their association with TSLP-induced GATA3+ Tregs in human melanoma." (PMID 36107619, 2022). "Only GATA3 was significantly associated with melanoma survival." (PMID 34301206, 2021). "A similar subset of GATA3+ Tregs was also found in skin biopsies from patients with primary human melanoma." (PMID 40873585, 2025). "Keratinocyte-derived thymic stromal lymphopoietin (TSLP) can also suppress cytotoxic T-cells to promote the growth and metastasis of melanoma by promoting GATA binding protein 3 (GATA3) expressing Tregs." (PMID 40872475, 2025). "In an alternative comparison, among the FOXP3+CD4+ Tregs, the percentage of GATA3+ cells was elevated in invasive melanoma compared with in situ melanoma." (PMID 36107619, 2022). "A Treg population in CD4+ T cells from human melanoma exhibits expression of GATA3 and other signature genes." (PMID 36107619, 2022). "To further explore the nature of GATA3+Foxp3–, GATA3+Foxp3+, and GATA3–Foxp3+ cells, we examined additional markers for Treg and Th2 cells in ILNs draining Braf/Pten/Tslp+/+ dorsal melanomas." (PMID 36107619, 2022). "Metastatic melanoma with aberrant expression of GATA3 and focal weak expression of pan cytokeratin was reported in one case report." (PMID 34449584, 2021). "These cells, thus, resemble the GATA3+ Tregs identified in mouse melanoma." (PMID 36107619, 2022). "An analogous population of GATA3-expressing Tregs was also identified in human melanoma tumors." (PMID 36107619, 2022). "TSLP-dependent accumulation of GATA3+ Tregs in melanoma tumor sites." (PMID 36107619, 2022). "Genetic ablation of TSLP reduces GATA3+ Tregs in LNs draining Braf/Pten melanoma." (PMID 36107619, 2022). "Since OX40 represented a marker for GATA3+ Tregs in Braf/Pten mice, we further examined whether this was the case for human melanoma." (PMID 36107619, 2022). "Moreover, the therapeutic response can be affected by several parameters, such as the mutational load of GATA3+ cells, FOXP3+ cells and CD33+ cells and the abundance of TILs in lung cancer or melanoma." (PMID 34221962, 2021). "GATA3 is useful for differentiating metastatic UC from other primary or secondary epithelial neoplasms, including adenocarcinoma and squamous cell carcinoma, as well as sarcoma and melanoma." (PMID 28144859, 2017). "Interestingly, a similar population of GATA3+ Tregs was also found in human melanoma." (PMID 40873585, 2025). "We then investigated whether GATA3+ Tregs were present within the human primary melanoma TME." (PMID 36107619, 2022). "Loss of terminal differentiation traits, as observed by inactivation of ESR1, PTPRS, or the metastasis suppressor gene GATA3, may reflect the intrinsic capacity of melanoma cells to gain plasticity, and to progressively acquire changes that trigger metastatic dissemination." (PMID 28578692, 2017). "For example, early-stage melanomas often express high levels of the immune modulator CD24 and the transcription factor GATA3, whereas progressed melanomas exhibit upregulation of the melanoma antigen family A (MAGE) antigens of unknown function, and cell cycle regulators such as CDK2." (PMID 19949544, 2009).
melanoma (continued). "In contrast, in invasive primary melanoma biopsies, we observed many more CD4+ cells, among which we identified GATA3+FOXP3– cells, GATA3–FOXP3+ cells, and GATA3+FOXP3+ cells." (PMID 36107619, 2022). "In Braf/Pten melanoma-draining LNs, TSLP promoted not only GATA3+ Th2 cells, but also GATA3+ Tregs expressing a specific signature including ST2, CCR8, ICOS, PD-1, CTLA-4, OX40, and IL-10 — but not Th2 cytokines IL-4 and IL-13." (PMID 36107619, 2022). "Human TH2-like Tregs (GATA3+CCR4+) have the highest chemotaxis, viability and suppressive function, and are enriched in melanoma and colorectal cancer." (PMID 34177968, 2021). "GATA3 promotes invasive behaviours of HNSCC and melanoma cells in vitro and in immunodeficient mice." (PMID 28263977, 2017). "We find that primary basal cell carcinomas, squamous cell carcinomas and thin melanomas express dramatically higher levels of many genes, including SPRR1A/B, KRT16/17, CD24, LOR, GATA3, MUC15, and TMPRSS4, than metastatic melanoma." (PMID 18442402, 2008). "Immunohistochemical studies showed diffusely positive SOX10, Melan-A, HMB-45, preferentially expressed antigen in melanoma (PRAME) and patchy S100 immunoreactivity and were negative for p63 and GATA3, supporting the diagnosis of melanoma." (PMID 39363663, 2025). "Additionally, negative staining for NKX2.2, CD99, desmin, S100, SOX10, HMB45, GATA3, CD45 (LCA), CD3, and CD20 further excluded diagnoses of Ewing sarcoma, rhabdomyosarcoma, melanoma, and the majority of non-Hodgkin lymphomas." (PMID 39404971, 2024). "Moreover, GATA3+ Tregs were found enriched in invasive primary melanoma, suggesting similar TSLP-driven immunosuppressive mechanisms in human melanomas." (PMID 39201498, 2024). "Indeed, examination of CRLF2 gene expression in CD4+ T cells from human melanoma scRNA-seq data did not reveal higher expression of CRLF2 by GATA3+ Tregs compared with other CD4+ T cells." (PMID 36107619, 2022). "In addition, we identified a potentially novel role for TSLP, via TSLP receptor (TSLPR) expressed by DCs, in promoting a subset of GATA3-expressing Tregs, and we uncovered a potentially new facet to how TSLP regulates melanoma progression through programming TME." (PMID 36107619, 2022).